CD4 (CD4 molecule)
Diseases named in the same sentence as CD4 in open-access papers (continued):
Sharing a sentence is not in itself a finding about the gene and the disease.
tumor (continued). "At last, we found a significantly different tumor-infiltrated lymphocytes feature, including lower abundance of CD4+ naive T cells in the samples with high-IPR signature." (PMID 35372049, 2022). "Increased CD4 + T cell infiltration can enhance the formation of a tumour inhibitory immune microenvironment and lead to a poor prognosis." (PMID 36100894, 2022). "A remarkably decreased number of FoxP3-expressing and IL-10-producing CD4+ Tregs were observed in the tumors of 4T1+d-MAPPS-treated animals compared to tumor-bearing animals that received saline (p < 0.05)." (PMID 35757015, 2022). "TLR7/8 agonist imiquimod was proven to activate NK cells to kill tumor cells and induct tumor-specific CD4+ T cells, resulting in a strong regression of low MHC-I tumors." (PMID 35413927, 2022). "CD4+ T cells can achieve anti-tumor efficacy through a variety of mechanisms, including enhancing antigen presentation and promoting T cell homing and T cell activation." (PMID 35748951, 2022). "As the main types of tumor-infiltrating lymphocytes (TIL), CD8 and CD4 T cells are deeply implicated in the cellular immune response." (PMID 35178106, 2022). "Flow cytometry measurements for group 6 showed a significant increase in tumor-infiltration of CD4+ and CD8+ T cells in both primary and distant tumors." (PMID 33402702, 2021). "In vivo transfer of peripheral CD4+ T cells provided a more durable tumour regression compared with peripheral CD8+ T cells, in contrast to previous studies." (PMID 34141724, 2021). "In tumor samples, we found that CD8+ T cells were positively associated with activated memory CD4+ T cell, follicular helper T cell, and M1 macrophage cells, indicating the cooperation among these cells." (PMID 33816503, 2021). "We did not detect any difference in the percentage of F4/80+ macrophages, Ly6C+ monocytes, B220+ B cells, Nk1.1+ NK cells, CD4+ or CD8+ T cells among CD45+ immune cells in the tumor." (PMID 34099731, 2021). "RT-PCR analysis revealed that these tumor-infiltrating macrophages expressed higher levels of transcripts encoding IL-1β, IL-12, IL-23, and TNF-α in the AAA-CD4+ group than in the control or auto-CD4+ groups." (PMID 34625113, 2021). "Meanwhile, they found that higher CD8+T and CD4+T infiltration corresponded to higher PD-1/PD-L1 expression, stronger tumor invasiveness and worse survival." (PMID 34925244, 2021). "Cytokine production within the GC TME arises from multiple sources, including downstream targets of H. pylori virulence factor CagA, host immune cells and especially CD4+ T-cells, and tumour cells." (PMID 34944729, 2021). "These immune cell subsets block anti-tumor activity of natural killer (NK) cells and effector CD4+ and CD8+ T cells." (PMID 34439292, 2021). "Flow cytometry showed that the ratios of tumor-infiltrating CD4+ and CD8+ T lymphocytes were significantly elevated in the CXCL13-overexpressing tumor, compared with parental 4T1 and 4T1-pCDH." (PMID 35693216, 2021). "Adaptive immunity, involving CD8+, CD4+T cells, and B cells, drives a tumour-specific response aimed at eradicating tumour cells, and contributes to the development of an immunological memory potentially protecting from tumour recurrence." (PMID 34073106, 2021). "Genetic depletion of CD4+ T cells increased tumor infiltrating CD8+ T cells and up-regulated their capacity to produce IFN-γ and granzyme B, therefore inhibiting tumorigenesis in a GEMM of PDA in a CD8+ T cell-dependent manner." (PMID 34290984, 2021). "For instance, Ramachandran and colleagues showed that upon tumor establishment, MDSCs accumulate in the BM of MM-bearing mice, and this was accompanied by the inhibition of anti-tumor cytotoxicity and a decrease in the presence of Th1 CD4+T cells." (PMID 33562441, 2021). "These unique tumour-infiltrating CD4+ T cells expressed the transcription factor BHLHE40, the effector cytokine IFNG, and the chemokine receptor CXCR5." (PMID 32457487, 2021).
tumor (continued). "Regulatory T cells (Treg cells) are a specific class of CD4+ T cells that are thought to promote tumor growth and invasion by inhibiting the host’s immune response and pro-inflammatory responses." (PMID 34654443, 2021). "The increased infiltration of CD4+ GzmB+ T cells in the central tumor area contributed to a better prognosis in the NCT group." (PMID 34631551, 2021). "This was in contrast with PD-1 expression, which was high on both tumor-infiltrating CD4+ and CD8+ T cell subsets." (PMID 33665363, 2021). "Several studies illustrated Salmonella’s ability to increase the tumor-infiltration of different innate and adaptive immune cells, including macrophages, natural killer (NK) cells, CD4+ helper T cells, CD8+ cytotoxic T cells, and B cells." (PMID 34203478, 2021). "Further, oncolytic HSV in combination with gemcitabine has shown to effectively suppress MDSCs and result in tumor regression and enhanced oncolysis accompanied by antitumor CD4+ and CD8+ T cell responses." (PMID 33920168, 2021). "The results showed that the proportion of tumor-infiltrating immune cells (activated memory CD4 T cells, resting dendritic cells, and neutrophils) was negatively correlated with the patient risk score." (PMID 34276767, 2021). "In tumor epithelium and stroma, most CD4+ T cells identified had either a Th2 (GATA-3+CD3+CD8-) or Treg (FOXP3+CD3+CD8-) phenotype, whereas only low numbers of Th1, Th17, and Tfh cells were observed." (PMID 34868011, 2021). "Scholars have reported that CD4+ T cells are critically vital in mediating tumor cell killing via multiple pathways." (PMID 34517904, 2021). "CD4+CD25++Tregs suppress the anti-tumour immune response either in the draining lymph nodes or in tumour tissue." (PMID 33995362, 2021). "Α 4-1BB caused a significant up-regulation of killer cell lectin-like receptor G1 (KLRG1) on CD8+, and less extent the up-regulation of effector T-cells and CD4+ in the tumor." (PMID 34267616, 2021). "Meanwhile, tumor-promoting cells like naive CD4+ T cells, macrophage Mo cells, and activated mast cells were detected in high-risk rather than low-risk group patients." (PMID 34880875, 2021). "In contrast, overexpressing BATF in CD8+ T cells enhanced effector function and resulted in improved tumor control, bypassing the need for CD4+ helper T cells." (PMID 33809259, 2021). "Collectively, the decreased and impaired CD4+ TILs were observed in tumor tissue, which triggered the impaired activation of CD8+ TILs, and correlated with poor prognosis in HCC." (PMID 34566989, 2021). "The methylation changes also resulted in transcriptomic changes with 341 differentially expressed genes in CD4+ tumor infiltrating T-cells compared to blood." (PMID 34012510, 2021). "We then checked that the expression level of MSMO1 was positively correlated with tumor purity, obtaining CD4 + T cells, a factor related to the cumulative survival rate of CESC over time." (PMID 34759952, 2021). "A high CD4+ T cells over CD8+ T cells imply the higher portion of HCC-specific CD4+ T cells, functional T cells against tumor, whereas the infiltrated Tregs functionally inhibit anti-tumor response, which can lead to poor prognosis after LT." (PMID 34638613, 2021). "The observation that CD4+ T cells synergise with CD8+ T cells in the immune response against tumours also extends to CAR T cell adoptive immunotherapy." (PMID 32457487, 2021). "SGPP1 and PLPP3 expression show a strong positive correlation with tumor-infiltrating dendritic cells (DCs), CD4+ and CD8+ T cells, neutrophils, and macrophages in the TNBC subtypes." (PMID 34235182, 2021). "The results showed that infusion of low-dose decitabine-pretreated CD4+ T cells significantly inhibited tumor growth and prolonged survival as compared to control CD4+ T cells." (PMID 33791306, 2021). "These functions by CD4+ T cell-induced changes on dendritic cells are key in shaping the cross-priming required for effective activation of anti-tumor CD8+ T cells." (PMID 33708224, 2021).
tumor (continued). "Our study reveals the significant depletion of tumor-infiltrating B cells, CD4+ TFH-like cells, and CD8+ TRM-like cells in EGFR-MT tumors." (PMID 34663810, 2021). "Germ-free and antibiotics-treated mice experienced a compromise in their immunologic response against tumors, with a significant decrease in tumor-infiltrating lymphocytes and effector CD4+ T-cells compared to the control group." (PMID 34360802, 2021). "LIMK1 expression had correlations with tumor purity (r = −0.189, P = 2.37e-05), CD4+ T cell (r = 0.285, P = 1.65e-10), macrophage (r = 0.143, P = 1.64e-03), neutrophil (r = 0.263, P = 4.53e-09), dendritic cell (r = 0.363, P = 1.20e-16)." (PMID 34149814, 2021). "T helper type 1 (Th1) cell is a major lineage of CD4+ effector T cell that enhances T cell-mediated immunity, and thus can control tumor growth." (PMID 33754054, 2021). "RT+CpG+OX40 increased the ratio of tumor-infiltrating effector T cells to T regulatory cells and significantly increased CD4+ and CD8+ T cell activation in the tumor draining lymph node (TDLN) and spleen." (PMID 34868010, 2021). "Only high densities of CD4+ (P < 0.001 and P = 0.001) and CD8+ (P < 0.001 and P = 0.015) tumor-infiltrating lymphocytes were associated with tumor stage in both dMMR and pMMR CRC." (PMID 33818637, 2021). "The CD4+ Th cells modulate tumor microenvironment by secreting cytokines such as IFN-γ, TGF-β, IL-4, IL-5, and IL-6." (PMID 33995619, 2021). "In order to associate the unique DNA methylation pattern observed in GBM infiltrating CD4+ T cells with its transcript profile, we performed RNA sequencing (RNAseq) analysis of CD4+ T-cells isolated from both tumor and blood samples of same five GBM patients." (PMID 34012510, 2021). "Further studies conducted in mouse tumor models indicate an activation of CD4+ T cells, which again stimulated DCs to express IL-12." (PMID 33141285, 2021). "We concluded that introduction of transgenic CD8α receptor in combination with Vγ5Vδ1TCR derived from clone FE11 allowed reprogramming of CD4+ T cells towards HLA-A*24:02-expressing tumor cells in vitro, though activity was lower when compared to CD8+ TEG011." (PMID 34759930, 2021). "Immune cells in the TME include T lymphocytes (CD4+ T lymphocytes and CD8+ T lymphocytes), natural killer (NK) cells, tumor-associated macrophages (TAM), dendritic cells (DC), myeloid-derived suppressor cells (MDSC), regulatory T cells (Treg), and neutrophils." (PMID 34084160, 2021). "In contrast to TH1 cells and CTL, TH2 and Treg represent CD4+ T cell subsets that facilitate tumor progression by exerting immunosuppressive activities within the TME." (PMID 33859645, 2021). "The infiltration of CD4+ GzmB+ T cells in the tumor center had a significant prognostic value, positively correlated with good OS and DFS." (PMID 34631551, 2021). "Despite these encouraging early findings, the fundamental role of CD4+ T cells in orchestrating anti-tumour responses was until recently eclipsed by the clinical success of CD8+ T cell-based immunotherapies." (PMID 32457487, 2021). "PD-1 and PD-L1 expression associates with CD4+, CD8+ and FOXP3+ tumor infiltrating lymphocytes related to poor survival in CCRCC." (PMID 33562338, 2021). "At the same time, CD4 T cells can have cytotoxic activity and during adoptive transfer experiments in mice, they can induce an anti-tumor response." (PMID 33498483, 2021). "The changes of immune cells in tumor tissues consisted of an increase in the number of CD4+ cells, CD8+ cells, CD3+ cells, and NK cells immediately after RFA." (PMID 34616914, 2021). "Concurrently, findings from preclinical mouse models also highlight a larger, more fundamental role for CD4+ T cells in anti-tumour immunity than was previously thought." (PMID 32457487, 2021). "CD4+ T cells and Tregs exhibited similar levels of infiltration in all groups, but PD-1 blockade treatment decreased the tumor CD45+ F4/80+ macrophage infiltration." (PMID 34452929, 2021).
tumor (continued). "The specific contribution of cytotoxic CD4+ T cells in direct anti-tumor cytotoxicity in an immune-competent scenario with the presence of other cytotoxic effectors remains to be determined." (PMID 34910940, 2021). "CD4+ T cells, moreover, were superior in infiltrating and in proliferating in tumor tissue, highlighting their importance in the local antitumor immunity." (PMID 33546283, 2021). "In non-small cell lung cancer (NSCLC), we have previously showed that a high density of B cells within TLS (TLS-B cells) is positively correlated with tumor antigen-specific antibody responses and increased intratumor CD4+ T cell clonality." (PMID 33763071, 2021). "The first major turning point began in the mid-2000s when mouse models of cancer demonstrated that CD4+ T cells were necessary to maintain and sustain anti-tumour CD8+ CTL responses." (PMID 32457487, 2021). "If stromal cells are the main source of TNFα within the tumor, CD4 T cells also produce TNFα in sufficient amount to inhibit CD8 T cells anti-tumor response but insufficient to impact tumor cells proliferation or viability." (PMID 33498483, 2021). "Assessment of the immune landscape in the ascites showed the predominance of CD8+, CD4+, B–, and memory T cells, among others, and the coexistance of different immune cell types within the same tumor microenvironment." (PMID 34709744, 2021). "In our research, the Fstl1+/- mice had the same volume of primary tumor as the WT mice; however, IHC staining showed that the number of infiltrated CD4+ T cells in the primary tumor was significantly decreased in Fstl1+/- mice compared to that in WT mice." (PMID 33639614, 2021). "Rosiglitazone limited the accumulation of early MDSCs and Tregs but increased circulating CD8+ T cells and intratumoral CD4+ and CD8+ T cells to change tumor-associated immunosuppressive mediators, thereby enhancing the effect of gemcitabine." (PMID 33413697, 2021). "Through immunohistochemistry, both CD8+ effector memory cells and polyfunctional CD4+ T cells were observed in abundance among tumor infiltrating lymphocytes (TILs)." (PMID 33669271, 2021). "Phenotypic analysis by flow cytometry of TILs from B16/F10-challenged tumor suggests that LILRB4+CD4+ T cells expressed higher surface LAP/TGFβ compared with LILRB4−CD4+ T cells." (PMID 33974041, 2021). "Further, using global systemic immune cell profiling by CyTOF and single cell RNAseq in tumor bearing animals undergoing immunotherapy, a peripheral CD4 T cell cluster was identified as being sufficient to mediate antitumor response." (PMID 34064410, 2021). "CD4 + Th1 and Th17 cells have been well documented to activate cytotoxic T lymphocytes, whereas Tregs inhibit efficacious anti-tumor responses." (PMID 34222240, 2021). "We observed that B. longum 420 combined with anti-PD-1 antibody significantly increased the numbers of tumor-infiltrating CD4+ and CD8+ T cells in vivo." (PMID 34589578, 2021). "After 30 weeks of exposure, this increase in CD4+CD25+ regulatory T-cells was significantly reduced in UVB-exposed tumor bearing mice treated with TAK-242 compared to UVB-exposed mice treated with vehicle after 30 weeks of exposure." (PMID 34771569, 2021). "A role for irradiated tumor-primed DCs in the prevention of local tumor growth involving CD4+ and CD8+ T cells was shown much before the introduction of the concept of ICD." (PMID 34068491, 2021). "Approximately 85% of the tumours had a high expression of CD204+TAMs with a low expression of CD4+TILs." (PMID 35201470, 2021). "These responses include increased tumor infiltration by CD4+ and CD8+ effector T cells and memory T cells." (PMID 34575893, 2021). "In this sense, CD4+ CTLs have been identified during aging, chronic viral infections, and in anti-tumor responses." (PMID 34386013, 2021). "In particular, TILs from tumours T6 and T7 had higher polyfunctionality of both CD4+ and CD8+ T lymphocytes than TILs from the T3 and T4 tumours." (PMID 34503115, 2021).
tumor (continued). "Recent studies have demonstrated that blocking TGF‐β signaling in CD4+T cells remodeled the tumor microenvironment and restrained cancer progression and depletion of transforming growth factor‐β receptor 2 (TGFBR2) in CD4+ T cells promoted cancer progression." (PMID 33837660, 2021). "DMHCA reduced tumor progression, tumor multiplicity and fibrosis, and improved immune surveillance by reducing infiltrating myeloid-derived suppressor cells and increasing CD4 and CD8 effector T cells." (PMID 33780491, 2021). "Flow cytometry analysis revealed that HBO uplifts the infiltrations of lymphocytes, T cells, CD8+ T cell, and CD4+ T cell into the tumor bed of orthotopic H22 tumors." (PMID 34085419, 2021). "CD4 T cells can play various critical roles in sustaining an anti-tumor microenvironment, helping NK and CD8 T cell survival and cytotoxicity as well as B cell responses." (PMID 33717196, 2021). "It has been reported that in the tumor microenvironment, tumor cells can recruit immunosuppressive cells, such as CD4+ T cells, to disrupt the cytotoxic functions of CD8+ T cells." (PMID 34911533, 2021). "On the other hand, the TGF-β signaling pathway is critical in promoting CD4+ T cells differentiated into Tregs which enhance tolerance to tumor antigens and promote immune evasion." (PMID 33816258, 2021). "One preclinical tumour model investigating niraparib with anti-PD1 checkpoint inhibitors showed increased interferon pathways and enhanced infiltration of CD8+ cells and CD4+ cells in tumour cells, resulting in synergistic anti-tumour activity." (PMID 34572747, 2021). "In conclusion, CD4+ T cells responding to tumor-specific neoepitopes play an important role in mediating anti-tumor immune responses." (PMID 35097027, 2021). "As expected there was no expression of NFAT5 at the end of three high salt stimulation cycles in the CD4+T cells obtained from day 21 DLNs of tumor bearing CD4+NFAT5-KO mice." (PMID 33918403, 2021). "Current studies have shown that CD4+T cells mediate anti-tumor responses through a variety of mechanisms, such as the CCR5 ligand that acts as the center of CD4+ and CD8+T cell activation." (PMID 34090476, 2021). "IL-18 drives IFN-γ production to increase tumor immunogenicity and reinforces NK and CD4+ T cells immune responses and generates protective CD8+ T cells responses from recidivism." (PMID 33510147, 2021). "Tumor-infiltrating CD4 + T cells, CD8 + T cells, tumor-associated macrophages (TAMs), and neutrophils were associated with patient prognosis and tumor chemosensitivity." (PMID 34307347, 2021). "Of note, the authors show that IFN-γ production in the TME by revitalized CD4+ cells drives polarization of newly arrived monocytes into iNOS+ pro-inflammatory macrophages, which contribute to tumor rejection." (PMID 33777008, 2021). "Based on the analysis of online database TIMER (Tumor IMmune Estimation Resource), we found that GOLT1B was significantly associated with the infiltration of CD4+ T cells, CD8+ T cells and macrophages." (PMID 34059062, 2021). "In this patient, after anti-PD-1 exposure, the tumor microenvironment appeared predominantly composed with CD4+ helper T lymphocytes." (PMID 34771650, 2021). "A significant decrease in the number of CD4+ CD25+ Foxp3+ TILs in the tumor site was observed in the liposomal peptide plus CpG-ODN treated group." (PMID 34282215, 2021). "The same authors demonstrated that NK-92-TN cells inhibited the differentiation of human naïve CD4+ T cells to Tregs and decreased tumor volumes in vivo in a hepatocellular carcinoma xenograft cancer model." (PMID 34025641, 2021). "For example, CD8+ cytotoxic T cells, natural killer cells, CD4+ T helper cells, and M1 macrophages have antitumor roles, whereas Treg cells, M2 macrophages, and MDSCs assist in tumor immune evasion." (PMID 34762599, 2021).